CBLN3 (cerebellin 3 precursor)
Description:
May be involved in synaptic functions in the CNS.
Synonyms: PRO1486
Tractability: Antibody: UniProt places it where antibodies can reach, with medium confidence; UniProt predicts a signal peptide or a membrane-spanning region; its Gene Ontology location is reachable by antibodies, with medium confidence.
Gene: Protein-coding gene on chromosome 14 (24,423,886 to 24,430,972, reverse strand). Ensembl gene ENSG00000139899.
Subcellular location: Endoplasmic reticulum; Golgi apparatus, cis-Golgi network; Secreted; Synapse
Subcellular location (Human Protein Atlas): Nucleoplasm; Predicted to be secreted
Gene Ontology:
Biological process: maintenance of synapse structure; trans-synaptic signaling, modulating synaptic transmission; trans-synaptic signaling by trans-synaptic complex, modulating synaptic transmission
Cellular component: synapse; synaptic cleft; endoplasmic reticulum; extracellular region; Golgi apparatus; parallel fiber to Purkinje cell synapse
Genetic constraint (gnomAD): Loss-of-function variants: 14 observed, 17.22 expected, observed/expected ratio (o/e) 0.81, 90% interval 0.54 to 1.27. The upper end of that interval is the gene's LOEUF score, 1.27, which puts it in group 5 of 6, group 1 being the genes least tolerant of losing a copy. Missense variants: 263 observed, 270.2 expected, observed/expected ratio (o/e) 0.97, 90% interval 0.88 to 1.08. Synonymous variants: 129 observed, 117.15 expected, observed/expected ratio (o/e) 1.1, 90% interval 0.95 to 1.27.
Homologues: Orthologues: dog CBLN3 (94% identical), pig CBLN3 (94% identical), rabbit CBLN3 (93% identical), guinea pig CBLN3 (91% identical), rat Cbln3 (89% identical), mouse Cbln3 (89% identical), macaque CBLN3 (78% identical), zebrafish cbln12 (54% identical), zebrafish si:dkeyp-74b6.2 (52% identical), zebrafish cbln5 (23% identical), zebrafish cbln7 (23% identical), zebrafish cbln13 (22% identical), and 11 more. Paralogues in human: CBLN2 (53% identical), CBLN1 (53% identical), CBLN4 (53% identical).
Diseases named in the same sentence as CBLN3 in open-access papers:
CBLN3 is named in the same sentence as 4 diseases in open-access papers, as found by Europe PMC text mining. Sharing a sentence is not in itself a finding about the gene and the disease.
CBLN3 shares sentences with these, for which no sentence is quoted: Ataxia (1 paper); autism (1); cancer (1); hearing loss (1).